MYC (MYC proto-oncogene, bHLH transcription factor)
Diseases named in the same sentence as MYC in open-access papers (continued):
Sharing a sentence is not in itself a finding about the gene and the disease.
high grade B-cell lymphoma (3 papers, 2024). A term that refers to high grade B-cell lymphoma, not otherwise specified or high grade B-cell lymphoma with MYC and BCL2 and/or BCL6 rearrangements. "Beyond clinical characteristics, molecular features associated with DLBCL prognosis include cell-of-origin (COO) and MYC, BCL2, or BCL6 translocation status, or MYC “double hits (DH)”, with DH-DLBCL now considered as a distinct entity, High Grade B Cell Lymphoma (HGBCL)." (PMID 38902256, 2024). "Differentiating DLBCL NOS from other LBCL types, particularly from DLBCL/high-grade B cell lymphomas (HGBL) with MYC/BCL2 rearrangements (double hit), typically involves morphological assessment, immunophenotyping, and fluorescence in situ hybridization (FISH) for BCL2, BCL6, and MYC rearrangements." (PMID 38927948, 2024).
Huntington disease (3 papers, 2022 to 2025). Huntington disease (HD) is a rare neurodegenerative disorder of the central nervous system characterized by unwanted choreatic movements, behavioral and psychiatric disturbances and dementia. "Globally, by Ingenuity Pathway Analysis, the PNGT3-high hits featured the activation of the EIF2 pathway (p = 5.64e−09) microRNA biogenesis (p = 7.93e−08) and Huntington’s disease signaling (p = 5.73e−07) pathways, and the MYC transcriptional program activation (p = 5.3e−15)." (PMID 38316783, 2024).
infertile (3 papers, 2015 to 2023). "We further analyzed the data comparing CTRL vs. ID + UMI and found that MYC (Myc proto-oncogene protein) was the transcription factor associated with more proteins differentially expressed between control and infertile individuals." (PMID 37892144, 2023).
laryngeal squamous cell carcinoma (3 papers, 2011 to 2022). A squamous cell carcinoma that arises from the larynx. "MYC target 1 (MYCT1), also known as MTLC, is a direct target gene of c-Myc, and it has been first cloned from laryngeal squamous cell carcinoma (LSCC)." (PMID 30283340, 2018). "MYC target 1 (MYCT1), a direct target gene of c-Myc, is a novel candidate tumor suppressor gene first cloned from laryngeal squamous cell carcinoma." (PMID 30283340, 2018).
liver tumor (3 papers, 2017 to 2023). "MYC overexpression is a significant genetic event in pediatric liver tumors including pediatric HCCs." (PMID 37414763, 2023). "In our study, we examined the influence that FOXP3 had on MYC expression as well as the viability and the proliferation capacity of liver tumor cells in contrast with the adjacent tissues." (PMID 30378283, 2018). "Since miR‐198/FOXP3 has a strong suppression on tumor cells, more powerful alternative inhibitors that direct at these two sites could be developed to better inhibit the proto‐oncogene MYC expression for clinical liver neoplasm treatment." (PMID 30378283, 2018). "MiR‐198 inhibited cancer by suppressing the expression of MYC in liver neoplasm." (PMID 30378283, 2018). "MYC is a transcriptional factor that contributes to liver tumor maintenance." (PMID 29228658, 2017). "Our study aimed to explore the effects of FOXP3 expression on liver neoplasms cells and to further investigate the relationship between FOXP3 and proto‐oncogene MYC." (PMID 30378283, 2018). "The pcDNA‐MYC group was designed for observing MYC‐overexpression's influence on liver neoplasm cells, and miR‐198 inhibitor+pcDNA‐FOXP3 group as well as miR‐198 mimics+pcDNA‐MYC group was set up to restore the effects of miR‐198 and MYC." (PMID 30378283, 2018). "In summary, FOXP3 is confirmed to have the capacity to suppress proto‐oncogene MYC in liver neoplasm by up‐regulating miR‐198 through binding to its promoter, while miR‐198 targets the 3′‐UTR of MYC mRNA to inhibit its translation." (PMID 30378283, 2018). "Western blot and immunohistochemistry validated MYC overexpression in non-neoplastic hepatocytes and liver tumor tissues at fetal (E17.5) and different postnatal stages, suggesting that MYC is activated in the fetal stage." (PMID 37414763, 2023).
lymphoblastic lymphoma (3 papers, 2017 to 2025). A lymphoma composed of immature small to medium-sized precursor lymphoid cells (lymphoblasts). "MYC expression in ALK+ lymphoblastic lymphoma (LBL) is upregulated, probably by the STAT3 dependent activation of the MYC promoter." (PMID 28375188, 2017). "While deregulated MYC has a central role in BL pathogenesis, transgenic mice expressing MYC in B-lymphocytes (Eμ-Myc) invariably develop lymphoblastic lymphomas but not BL unless other genetic abnormalities are present." (PMID 41154426, 2025).
lymphoid leukemia (3 papers, 2021 to 2022). A malignant lymphocytic neoplasm of B-cell or T-cell lineage involving primarily the bone marrow and the peripheral blood. "Indeed, ChIP and expression analyses have shown that SEC is directly associated with MYC expression in myeloid and lymphoid leukemias." (PMID 34372899, 2021).
myeloproliferative disease (3 papers, 2022 to 2023). "The disruption of MYC targets is also noteworthy, since MYC impairs myeloid differentiation and promotes the proliferation and survival of hematopoietic stem cells and multipotent progenitors to drive myeloproliferative neoplasms." (PMID 36611979, 2023).
ovarian endometrioid carcinoma (3 papers, 2012 to 2025). "We also studied the consequences of shRNA-mediated inhibition of CTNNB1 on MYC gene expression in the TOV112D human ovarian endometrioid carcinoma cell line that harbors a CTNNB1 oncogenic mutation leading to β-catenin/TCF dysregulation." (PMID 26528816, 2015).
pediatric cancer (3 papers, 2016 to 2021). "Aberrant activation of several oncogenic pathways, including MYC pathway, is a hallmark of many childhood cancers, including NB." (PMID 34565342, 2021). "In childhood cancer, aberrant expression of MYC and MYCN genes delineates a group of aggressive tumours responsible for a major proportion of pediatric cancer deaths." (PMID 27438153, 2016).
polyp (3 papers, 2021 to 2024). A usually exophytic mass attached to the underlying tissue by a broad base or a thin stalk. "This study suggests that the Oct4 and CD26 panel is a promising biomarker for distinguishing CRC from normal and polyp patients, whereas the c-MYC and CXCR4 panel may identify polyp and CRC from normal individuals." (PMID 34335790, 2021). "Here, we demonstrated that c-MYC and CXCR4 dysregulation can be used to detect the existence of polyp and CRC." (PMID 34335790, 2021). "More importantly, c-MYC and CXCR4 were able to identify polyp/CRC patients with AUC values of 0.73 and 0.73, respectively (p < 0.05)." (PMID 34335790, 2021). "We reperformed the ROC analysis for c-MYC, CXCR4, and their combination by including the patients who developed polyp during follow-up in the polyp and CRC groups." (PMID 34335790, 2021). "The c-MYC and CXCR4 panel was able to identify polyp/CRC patients with AUC of 0.88 (p < 0.001), with sensitivity and specificity of 84.4% and 92.3%, respectively." (PMID 34335790, 2021). "Here, our two-gene panel (c-MYC and CXCR4) showed a decent 80.0% sensitivity for identifying polyp patients, and the performance further increased to 83.3% when future polyp development was included." (PMID 34335790, 2021). "Our result suggested that the CXCR4 and c-MYC panel may identify both polyp and CRC samples, suggesting their involvement in polyp development and potentially in early carcinogenesis." (PMID 34335790, 2021). "The expression of both c-MYC and CXCR4 was significantly higher in those who developed polyp." (PMID 34335790, 2021).
primary immunodeficiency (3 papers, 2022 to 2023). "GSEA revealed that MYC targets, E2F targets, mTORC1 signaling, Wnt /β-catenin signaling and cell cycle were upregulated, and cell adhesion molecules, and primary immunodeficiency were decreased in high-risk group." (PMID 36807122, 2023). "In THYM, FAM72A was associated with G2M checkpoint, MTORC1 signaling, MYC targets v1, DNA replication, two DNA repair pathways, oxidative phosphorylation, and primary immunodeficiency." (PMID 36613817, 2022). "The KEGG enrichment functions of MYC include primary immunodeficiency, ErbB signaling pathway, adipocytokine signaling pathway, cell adhesion molecules cams, B cell receptor signaling pathway, leukocyte trans endothelial migration, intestinal immune network for iga production, oocyte meiosis." (PMID 37953920, 2023).
pulmonary hypertension (3 papers, 2013 to 2023). Increased pressure within the pulmonary circulation due to lung or heart disorder. "MYC mRNA stability may also be enhanced by the hypoxia-induced down-regulation of micro RNAs miR-449a-5p and let-7g, which contribute to hypoxia-induced proliferation of PASMCs in vitro and pulmonary hypertension in vivo." (PMID 37428010, 2023).
T-cell neoplasms (3 papers, 2022 to 2024). "Here, we showed that pERK, MYC, and pSTAT3 were differentially expressed in different T-cell neoplasms." (PMID 38339397, 2024). "In T-cell neoplasms, a previous study showed that EZH2 expression was correlated with the expression of MYC and/or pSTAT3 in a subset of T-cell neoplasms." (PMID 38339397, 2024). "The molecular basis underlying precursor T-cell neoplasms are highly heterogeneous and may involve deregulation of multiple signaling pathways such as NOTCH1, JAK/STAT, PI3K/AKT, MAPK/ERK, c-MYC or mTOR8–10." (PMID 39033228, 2024). "In the other T-cell neoplasms, there was a variable, but higher, co-expression of EZH2 with pERK, MYC, and pSTAT3." (PMID 38339397, 2024). "Immunohistochemical staining (IHC) was performed for EZH2, pERK, MYC, and pSTAT3 on 43 ATLL cases and 104 cases of other T-cell neoplasms." (PMID 38339397, 2024).
testicular cancer (3 papers, 2015 to 2022). A primary or metastatic malignant neoplasm that affects the testis. "Based on our and published data (Stewart 1984), MYC expression is silenced in normal SPCs but de-repressed in testicular cancer cells." (PMID 29527532, 2016). "On the other hand, MYC was co-expressed with CIP2A in testicular cancers." (PMID 29527532, 2016).
undifferentiated pleomorphic sarcoma (3 papers, 2013 to 2025). An undifferentiated soft tissue sarcoma characterized by the presence of a pleomorphic malignant cellular infiltrate. "We also identified similarities in gene expression between canine STS and human undifferentiated pleomorphic sarcoma, with MYC dysregulation in canine indicating poor prognosis." (PMID 41375061, 2025).
Waldenström Macroglobulinemia (3 papers, 2016 to 2024). "Finally, treatment with NSC12 triggered the downregulation of the signal adaptor protein MYD88 in Waldenström Macroglobulinemia (WM), reducing c-Myc protein levels and MYC signature activity." (PMID 39482742, 2024).
acute liver failure (2 papers, 2021 to 2024). Rapid deterioration of liver function causing encephalopathy and coagulopathy. "MYC is a “global” transcription factor that contributes to various diseases, including cancers, age-associated disorders, and acute liver failure, among others." (PMID 37450923, 2024). "All of these genes were regulated by the transcription factor MYC, suggesting that MYC is a master regulator of acute liver failure." (PMID 34419149, 2021). "Microbiome depletion attenuated the acute liver failure, suggesting that factors produced by the microbiome regulates the MYC cascade." (PMID 34419149, 2021).
amyloid (2 papers, 2013 to 2025). "A closer examination of the Amyloidosis GWAS results showed one distinct peak of association on chromosome 13 that was centered on FAM84B and MYC, both of which are known to be expressed in renal tissue." (PMID 24130694, 2013).
ankylosing spondylitis (2 papers, 2023). An autoimmune chronic inflammatory disorder characterized by inflammation in the vertebral joints of the spine and sacroiliac joints. "It has also been suggested that MYC may be an important bridge between inflammation and heterotopic ossification in ankylosing spondylitis." (PMID 37953920, 2023).
Atrophy (2 papers, 2008 to 2025). Any weakening or degeneration, especially through lack of use. "In this perspective, we think that our approach has given a good contribution: in fact we were able to identify some proteins and transcription factors, such as SMAD3/4, GNB2L1/RACK1, MYC, MAX and JUN whose functions have been studied extensively in tumours and in some atrophy models." (PMID 19108710, 2008).
autoimmune (2 papers, 2013 to 2019). "This mouse will allow us to investigate whether tissue expression of the antigen causes autoimmunity when c-MYC specific T-cells are administered." (PMID 24130880, 2013). "To address whether a therapeutic window exists between anti-tumor immunity of c-MYC-specific T-cells and autoimmunity, we have generated a humanized c-MYC mouse in which the endogenous murine c-Myc gene is replaced by the human c-MYC gene." (PMID 24130880, 2013). "In addition, several aspects remain that need further investigation: the most important concern is autoimmunity due to the expression of c-MYC in healthy, non-malignant proliferating tissues." (PMID 24130880, 2013).
bone sarcoma (2 papers, 2015 to 2023). A sarcoma that arises from the bone. "In contrast, in bone sarcomas, the amplification of MET and MYC was significantly associated with prognosis, and the prognosis of patients with amplification of these two genes was significantly worse than that of patients without amplification." (PMID 37546405, 2023). "In bone sarcomas, MET amplification (hazard ratio [HR] = 0.17, 95% confidence interval [CI]: 0.05–0.51, p < 0.001) or MYC amplification (HR = 0.2, 95% CI: 0.07–0.55, p < 0.001) were significantly associated with worse overall survival." (PMID 37546405, 2023).
breast ductal carcinoma (2 papers, 2018 to 2024). "We analyzed 70 cases of well characterized archival breast ductal carcinoma specimens from AA women for MYC oncogene amplification." (PMID 29523126, 2018). "In a meta-analysis of 29 studies of breast ductal carcinomas, MYC amplification, defined as 2-fold increase in gene copy number, was found in approximately 16% of cases." (PMID 29523126, 2018).
Cachexia (2 papers, 2015 to 2022). Severe weight loss, wasting of muscle, loss of appetite, and general debility related to a chronic disease. "However, the exact role of c-MYC in cachexia is not fully defined and will be evaluated by future studies." (PMID 26510913, 2015).
cervical (2 papers, 2012 to 2021). "The array data analysis performed with GEO2R showed that the expression of CBP/β-catenin and its target genes of KLF4, MYC, and SOX2 were upregulated, generally synchronicity with the progression of cervical lesion grade." (PMID 34257574, 2021).
choriocarcinoma (2 papers, 2022 to 2023). An aggressive malignant tumor arising from trophoblastic cells.
Crohn disease (2 papers, 2019 to 2022). A gastrointestinal disorder characterized by chronic inflammation involving all layers of the intestinal wall, noncaseating granulomas affecting the intestinal wall and regional lymph nodes, and transmural fibrosis. "Using CRISPR-Cas9, they found that rs6651252 enhancer regulates expression of the c-MYC, and they revealed that MYC expression levels are elevated in the Crohn’s disease patients." (PMID 35163260, 2022).
diabetic retinopathy (2 papers, 2021 to 2024). "In the context of diabetic retinopathy, MYC upregulation has been associated with increased expression of apoptotic genes and accelerated endothelial cell apoptosis." (PMID 39634176, 2024). "We performed bioinformatic analysis using public database data, which revealed the potential roles of MYC and SLC7A11 in diabetic retinopathy (DR)." (PMID 39634176, 2024). "This approach will allow us to observe their effects on mitochondrial function and cell apoptosis, providing a more comprehensive understanding of the roles of MYC and SLC7A11 in diabetic retinopathy and offering scientific evidence for disease prevention and treatment." (PMID 39634176, 2024).
endometrioid tumor (2 papers, 2016 to 2021). A benign, borderline, or malignant epithelial tumor of the female reproductive system characterized by the presence of glands and/or cysts lined by neoplastic cells that resemble endometrial cells. "However, c-MYC amplification had no impact on clinical outcome in serous and endometrioid tumors." (PMID 33718147, 2021).
fibrolamellar carcinoma (2 papers, 2023). "Fibrolamellar carcinoma and adenomyomatosis samples presented increased expression of Aurora kinase A, c-MYC, and ornithine decarboxylase when compared to normal liver, while ornithine transcarbamylase was decreased." (PMID 36788919, 2023). "(H) Schematic of DNAJ-PKAc mediating cell proliferation in fibrolamellar carcinoma (FLC) by increasing c-MYC expression by increased translation, with additional effects via GSK3B, AURKA, and PIM2." (PMID 36692000, 2023). "(F) Immunoblot showing the presence of DNAJ-PKAc and different level of c-MYC and n-MYC in fibrolamellar carcinoma (FLC) tumor samples (FLC) vs adjacent liver (N) from four FLC patients." (PMID 36692000, 2023).
ganglioneuroblastoma (2 papers, 2025 to 2026). A neuroblastic tumor characterized by the presence of neuroblastic cells, ganglion cells, and a stroma with Schwannian differentiation constituting more than fifty-percent of the tumor volume. "The case from the local cohort had a c-MYC amplification and died within a year of disease discovery, while the TARGET case had an unfavourable histology with the diagnostic category “Ganglioneuroblastoma, nodular”, but the patient was alive after > 10 years of follow-up (last follow-up)." (PMID 40713849, 2025).
germ cell tumor (2 papers, 2016 to 2021). A benign or malignant, gonadal or extragonadal neoplasm that originates from germ cells. "These in vivo and in vitro studies implicate MLX and other members of the proximal MYC network, such as MNT, in regulation of metabolism and differentiation, as well as in suppression of intrinsic and extrinsic death signaling pathways in both spermatogenesis and male germ cell tumors (MGCTs)." (PMID 34669700, 2021).
Gynecologic cancer (2 papers, 2016 to 2021).
iron deficiency (2 papers, 2021 to 2025). "While CPX iron chelation suppressed pathways associated with cell cycle (G2M checkpoint) and metabolic reprogramming (MYC targets), similar to iron deficiency, only 45 genes were found to be mutually differentially expressed." (PMID 40541943, 2025).
lactic acidosis (2 papers, 2025 to 2026). Metabolic acidosis characterized by the accumulation of lactate in the body. "Despite aggressive chemotherapy, including rituximab, the patient developed refractory lactic acidosis, linked to rapid tumor cell turnover and MYC-driven metabolic reprogramming." (PMID 41180747, 2025). "Metabolomics revealed that stretch-induced mitochondrial dysfunction in PASMCs caused lactic acidosis via enhancement of PDK1 (pyruvate dehydrogenase kinase 1) and c-MYC, leading to increased INHBA expression." (PMID 41568456, 2026).
leukoplakia (2 papers, 2017 to 2023). A white patch or plaque on a mucous membrane that cannot be characterized clinically or pathologically as any other disease. "Several pathways were actively enriched, including pathways involved in oral leukoplakia formation, embryonic germ cell pathways, the WNT/β-catenin signaling pathway, and pathways involved in the deregulation of MYC/E2F1 target genes." (PMID 36982384, 2023).